CACFD1 (calcium channel flower domain containing 1)
Description:
Transmembrane protein which mediates synaptic endocytosis and fitness-based cell culling. In response to different stimulus strengths, controls two major modes of synaptic vesicle (SV) retrieval in hippocampal neurons; Clathrin-mediated endocytosis (CME) in response to mild stimulation and activity-dependent bulk endocytosis (ADBE) in response to strong stimulation (By similarity). In cytotoxic T-lymphocytes (CTLs) facilitates calcium-dependent endocytosis of cytotoxic granules at the immuno synapse (By similarity). Different isoforms work as fitness fingerprints in 'loser' and 'winner' cells and thereby mediate win/lose decisions as part of the cell competition process. [Isoform 1]: Functions with the other flower isoforms to produce tissue-specific fitness fingerprints that identify unfit or fit cells during cell selection processes in order to maintain tissue health. During cell competition, if levels of this isoform in cells is higher than in the surrounding neighboring cells, the cells are recognized as 'winner' cells, and do not undergo elimination via apoptosis. [Isoform 2]: Functions with the other flower isoforms to produce tissue-specific fitness fingerprints that identify unfit or fit cells during cell selection processes in order to maintain tissue health. During cell competition, if levels of this isoform in unfit cells is higher than in the surrounding neighboring cells, the cells are recognized as 'loser' cells, and undergo elimination via apoptosis to be replaced by the surrounding healthy 'winner' cell population. [Isoform 3]: Functions with the other flower isoforms to produce tissue-specific fitness fingerprints that identify unfit or fit cells during cell selection processes in order to maintain tissue health. During cell competition, if levels of this isoform in unfit cells is higher than in the surrounding neighboring cells, the cells are recognized as 'loser' cells, and undergo elimination via apoptosis to be replaced by the surrounding healthy 'winner' cell population. [Isoform 4]: Functions with the other flower isoforms to produce tissue-specific fitness fingerprints that identify unfit or fit cells during cell selection processes in order to maintain tissue health. During cell competition, if levels of this isoform in cells is higher than in the surrounding neighboring cells, the cells are recognized as 'winner' cells, and do not undergo elimination via apoptosis.
Synonyms: C9orf7; D9S2135; flower
Tractability: Antibody: UniProt places it where antibodies can reach, with high confidence; UniProt predicts a signal peptide or a membrane-spanning region; its Gene Ontology location is reachable by antibodies, with medium confidence.
Gene: Protein-coding gene on chromosome 9 (133,459,965 to 133,470,848, forward strand). Ensembl gene ENSG00000160325.
Subcellular location: Cell membrane; Cytoplasmic vesicle, secretory vesicle, synaptic vesicle; Golgi apparatus; Vesicle; Cell membrane (Isoform 1); Early endosome; Recycling endosome; Endoplasmic reticulum membrane (Isoform 2)
Subcellular location (Human Protein Atlas): Nucleoplasm
Gene Ontology:
Molecular function: protein binding
Biological process: vesicle-mediated transport
Cellular component: early endosome; endoplasmic reticulum membrane; plasma membrane; recycling endosome; Golgi apparatus; vesicle; immunological synapse; membrane; synaptic vesicle
Genetic constraint (gnomAD): Loss-of-function variants: 26 observed, 18.53 expected, observed/expected ratio (o/e) 1.4, 90% interval 1.02 to 1.86. The upper end of that interval is the gene's LOEUF score, 1.86, which puts it in group 6 of 6, group 1 being the genes least tolerant of losing a copy. Missense variants: 265 observed, 218.59 expected, observed/expected ratio (o/e) 1.21, 90% interval 1.1 to 1.34. Synonymous variants: 121 observed, 98.4 expected, observed/expected ratio (o/e) 1.23, 90% interval 1.06 to 1.43.
Homologues: Orthologues: pig CACFD1 (94% identical), mouse Cacfd1 (93% identical), rabbit CACFD1 (92% identical), rat Cacfd1 (92% identical), guinea pig CACFD1 (88% identical), chimpanzee CACFD1 (86% identical), dog CACFD1 (68% identical), tropical clawed frog cacfd1 (67% identical), zebrafish cacfd1 (62% identical), Caenorhabditis elegans flwr-1 (27% identical), Drosophila melanogaster fwe (27% identical).
Diseases named in the same sentence as CACFD1 in open-access papers:
CACFD1 is named in the same sentence as 5 diseases in open-access papers, as found by Europe PMC text mining. Sharing a sentence is not in itself a finding about the gene and the disease. The quoted sentences say what the papers report.
COVID-19 (2 papers, 2023 to 2025). A disease caused by infection with severe acute respiratory syndrome coronavirus 2. "There are two SNPs in the CACFD1 gene that have been identified as factors that contribute to the genetic susceptibility for both COVID-19 and cardiovascular disease." (PMID 40002898, 2025). "The results of these genetic factors in the genes (TLR7, UNC13D, DES, SPEG, LZTFL1, ABO, ILRUN, and CACFD1) provide substantial insights into the genesis of cardiovascular issues linked with COVID-19." (PMID 40002898, 2025). "The SNP (rs10490770) located near LZTFL1 suggested direct causality (SNPs → COVID-19 → CHD), and SNPs in ABO (rs579459, rs495828), ILRUN(rs2744961), and CACFD1(rs4962153, rs3094379) may simultaneously influence COVID-19 severity and CHD risks." (PMID 37964352, 2023). "Shared genetic variants contributed to the causality, where rs10490770 in LZTFL1 suggested direct causality (SNPs → COVID-19 → CHD), and SNPs in ABO (rs579459, rs495828), ILRUN (rs2744961), and CACFD1(rs4962153, rs3094379) may simultaneously influence their risks." (PMID 37964352, 2023).
CACFD1 also shares sentences with these, for which no sentence is quoted: cancer (1 paper); cerebral malaria (1); glioma (1); tumor (1).